STAT6 (signal transducer and activator of transcription 6)
Diseases named in the same sentence as STAT6 in open-access papers (continued):
Sharing a sentence is not in itself a finding about the gene and the disease.
tumor (continued). "Here, we showed that STAT6 deficiency is necessary for controlling tumor growth in a model of CAC." (PMID 33919941, 2021). "Interestingly, we observed histological damage and tumor growth recovery during STAT6 deficiency, supporting the idea that Treg cells developed in STAT6−/− mice are protective against colon tumorigenesis." (PMID 33919941, 2021). "Thus, with STAT6 deficiency, an increased number of Treg cells induce resistance against tumorigenesis, arresting tumor-promoting inflammation." (PMID 33919941, 2021). "Besides NKX2-1, we identified that HNF1B, a previously reported tumor suppressor found in other cancer types, STAT6, and SP100 were inactivated and linked to many silenced enhancers in a subgroup of LUAD." (PMID 32925947, 2020). "To determine whether the increased sensitivity to DSS-induced inflammation and elevated tumor load in Stat6−/− mice was dependent on loss of Stat6 in hematopoietic cells or another cell compartment, we performed adoptive transfer experiments." (PMID 30353167, 2019). "Additionally, the activation of signal transducer and activator of transcription (STAT) family members (for example STAT6) is closely linked to tumor-promoting inflammation and the suppression of anti-tumor immunity in multiple cancer tissues." (PMID 31394811, 2019). "The DNA methylation and expression levels of PHYHD1, LTBR, MYBPHL, C22orf42, PRR5, ANKDD1A, RAB13, CAMKV, KIFC3, WNT4 and STAT6 are associated with tumor invasion, and these genes may become the potential genes for targeted therapy." (PMID 31796052, 2019). "Further analysis of functional pathways showed that the genes upregulated by STAT6 knockdown were the majority of cytokines, tumor suppressors, and molecules regulating MHC II-associated antigen processing and presentation, anti-apoptosis, chromosome stability, and cell migration." (PMID 30532138, 2018). "In this system, CEL could inhibit the STAT6 pathway and repolarize tumor‐associated macrophages from the M2 phenotype to the M1 phenotype, thus alleviating tumor immunosuppression, and exerting a synergistic and potentiating effect with LY2157299, which showed a good therapeutic effect on glioma." (PMID 40873643, 2025). "In addition, the inhibitory effect of TAM on tumor cell migration was associated with the blockade of the macrophage-specific immune checkpoint SHP1/SHP2, and reprogramming of the tumor-associated macrophages to the pro-inflammatory M1 phenotype via STAT6-inactivation." (PMID 35269804, 2022). "Additionally, Codiak Biosciences manufactures anti-cancer exosomes that deliver INF-γ, IL-12, or Stat-6 and express a surface protein to facilitate specific uptake by tumor-resistant APCs or selectively target M2-type-polarized, tumor-associated macrophages for the treatment of solid tumors." (PMID 33572657, 2021). "Moreover, the STAT6 knockdown could be linked to the decreased ability of PCa cell lines to migrate, an essential step in tumor migration and metastasis." (PMID 34638338, 2021). "In addition, tumors have been found to induce production of type II NKT cells, which in turn secrets IL-13, thereby not only causing aggregation of MDSC in the tumor microenvironment but also activating the STAT6 signaling pathway and suppressing CD8+ T cell function." (PMID 35111740, 2021). "Consequently, Stat3-deficiency in IEC reduced tumor growth in Stat6−/− mice." (PMID 30353167, 2019). "Targeting STAT6 or MTHFD2 suppressed tumor growth in TKIs-resistant patient-derived xenograft models." (PMID 41484064, 2026). "These analyses identified several differentially methylated genes linked to invasiveness (e.g., PHYHD1, WNT4, STAT6, CDH1, CDH13), aggressive behaviour (e.g., AIP, PDCD1, LINE-1), and tumour regrowth (e.g., TERT, FAM90A1, ING2)." (PMID 41866138, 2026).
tumor (continued). "IL4, secreted by Th2 cells, binds to IL4R on tumor cells, leading to activation of signal transducer and activator of transcription 6 (STAT6) and the subsequent upregulation of GATA3 and IL4 expression." (PMID 39941924, 2025). "Since the discovery of this molecular feature, testing for the NAB2-STAT6 fusion and STAT6 nuclear expression has been recommended in order to classify the tumor as SFT." (PMID 41007078, 2025). "The major vault protein significantly increased infiltration of M2-type tumor-associated macrophages in tumor tissues of HCC patients, promoting HCC proliferation, metastasis, and invasion through enhanced STAT6 activity." (PMID 41409600, 2025). "The study results suggest that when HT and PTC coexist, increased STAT6 expression promotes the polarization of M2 macrophages and regulates the tumor immune microenvironment, potentially enhancing tumor immune evasion." (PMID 40230479, 2025). "This process specifically activates the STAT6 signaling pathway and induces tumor-promoting M2 polarization of macrophages." (PMID 40612677, 2025). "CTHRC1 is a secreted protein that, once released into the tumor microenvironment, influences the immune landscape by activating the STAT6 pathway in macrophages." (PMID 40330466, 2025). "In tumor-associated macrophages originating from HCC patients, membrane transport proteins responsible for the absorption of zinc (Zip9) promoted STAT6 phosphorylation and M2 macrophage polarization and concomitant inhibition of M1 macrophage polarization." (PMID 41409600, 2025). "Sushrut Kamerkar designed the engineered exosome delivering an antisense oligonucleotide (ASO) targeting STAT6 (exoASO-STAT6), which selectively targeted tumor macrophages and produced potent antitumor activity." (PMID 41567219, 2025). "STAT6 expression in tumor cells can impact the formation and composition of the tumor microenvironment facilitating immune cell recruitment and macrophage polarization." (PMID 39936166, 2025). "Histopathological characterization and immunohistochemical staining, particularly CD34 in combination with Bcl‐2 and STAT6, are the basis for diagnosing this tumor." (PMID 41409894, 2025). "Studies have shown that in the tumor microenvironment, M2 macrophage polarization is regulated by various cytokines such as IL-4, IL-13, and the STAT6/C/EBPβ signaling pathways." (PMID 40433361, 2025). "This was demonstrated by increased DNA binding activity, phosphorylation of STAT6, and higher expression levels of IL-4, IL-4Rα, and p21 in their tumor tissues." (PMID 40636453, 2025). "The IL-4 transgenic mice displayed smaller tumor volumes and weights and showed enhanced activation of the STAT6 pathway." (PMID 40636453, 2025). "Upregulation of Bcl-2 and Bcl-xL via IL-4/STAT6 signaling is therefore a key mechanism by which tumor cells evade apoptosis and sustain their growth under therapeutic pressure." (PMID 40864740, 2025). "We performed IF and WB assays on key proteins of the PI3K/AKT/STAT6 pathways to elucidate the molecular mechanism by which QRHXF promotes metastasis in tumor cells and augments checkpoint immunotherapy." (PMID 40670983, 2025). "Immunohistochemical analysis revealed moderate diffuse membrane expression of the anti-CD34 antibody in the tumor cells, as well as moderate and diffuse nuclear expression of the anti-STAT6 antibody." (PMID 40065864, 2025). "The rarity of this tumor location necessitates heightened clinical suspicion and reliance on immunohistochemical markers like STAT6 for accurate diagnosis." (PMID 40343249, 2025).
tumor (continued). "In fact, estrogen suppressed tumor growth functions by inhibiting the JAK1/STAT6 signaling pathway that drives macrophage M2 activation, potentially explaining predominance of HCC in men compared to women." (PMID 41409600, 2025). "ASO therapies have been investigated targeting various oncogenes like STAT6 (Signal transducer and activator of transcription 6) which plays a role in tumor progression and immune evasion." (PMID 40428391, 2025). "In vivo, downregulation of CRNDE mitigated tumor volume, diminished the expression of key angiogenesis-related proteins and simultaneously suppressed the expression of STAT6 and its phosphorylation." (PMID 41409600, 2025). "Through STAT3 and STAT6 activation, IL-6 stimulates M2 macrophage polarization, tumor growth, and immune suppression." (PMID 41350724, 2025). "Conversely, upon administration of ADRB2 blockers, the expression level of KLF4, p-JAK1, and p-STAT6 was reduced, along with a decrease in the proportion of pro-tumoral macrophages in the tumor microenvironment." (PMID 40276761, 2025). "The IL-4/STAT6 axis plays a pivotal role in tumor development and the establishment of an immunosuppressive milieu." (PMID 40864740, 2025). "The results showed that the expression of KLF4, p-JAK1, and p-STAT6 was increased in the tumor tissue of the sleep deprivation group compared to the normal sleep group." (PMID 40276761, 2025). "In contrast, M2 polarization, associated with tumor promotion, is activated by signals like IL-4, IL-10, and TGF-β, primarily through the JAK/STAT6, PI3K/AKT/mTOR, and TGF-β/SMAD pathways, promoting tissue repair, immune suppression, and angiogenesis." (PMID 40330466, 2025). "This fusion gene promotes tumor cell proliferation and survival by activating the STAT6 signaling pathway." (PMID 40027120, 2025). "STAT6 was found to be diffusely and strongly positively expressed in tumor cells, which also supported the diagnosis of SFT." (PMID 39220647, 2024). "STAT proteins, especially STAT3 and STAT6, play critical roles in immune-suppression and tumor invasion." (PMID 39525474, 2024). "The regular STAT6 is frequently activated and expressed in tumor cells and regulates several genes crucial for cellular growth and proliferation, as well as inflammation and immune response." (PMID 39120790, 2024). "IL-4 and -13 receptors are up-regulated and activated in many tumours, including OC, which initiates the phosphorylation of Stat6, leading to increased tumour cell proliferation and resistance to apoptosis." (PMID 38974022, 2024). "On immunohistochemistry, the tumor cells were diffusely and strongly positive for STAT6, BCL2, and CD34." (PMID 39021462, 2024). "We found that STAT6 was diffusely and strongly positively expressed in tumor cells, which IHC also supported." (PMID 39220647, 2024). "By immunohistochemistry, STAT6 was the defining marker for the diagnosis, being positive in the tumor cells in all the cases." (PMID 38659562, 2024). "Since then, at least 12 distinct junctional breakpoints (between exons 2–7 on NAB2 and exons 2–22 on STAT6) of the NAB2-STAT6 fusion have been identified and are thought to account for pathological variation and tumor aggressiveness in SFTs." (PMID 38511173, 2024). "Compared to the primary tumor, the recurrent tumors showed a higher Ki67 proliferation rate as well as stronger expression of STAT6." (PMID 38341593, 2024). "The volume of tumor formation was significantly greater in the group overexpressing STAT6 compared to the control group." (PMID 39353898, 2024). "We observed strong nuclear and diffuse STAT6 immunoreactivity in tumor cells, along with diffuse positivity for CD34." (PMID 38388450, 2024). "In this context, the constitutively active STAT6 drives the expression of granzyme A, granzyme B, FasL and IFNγ proteins, which can be critical to donor T cell-mediated anti-tumor (GVT) immunity." (PMID 39796136, 2024).
tumor (continued). "In this study, we evaluate a STAT6 3′ UTR-targeting, single-stranded DNA ASOs, with the objective to downregulate the expression of all NAB2-STAT6 fusion transcripts, in an effort to exert anti-tumor benefits for SFTs." (PMID 38511173, 2024). "STAT6 is a transcription factor involved in tumorigenesis and the regulation of the tumor microenvironment." (PMID 38877472, 2024). "Immunohistochemically, the tumor cells were diffusely positive for STAT6 (nuclear expression pattern) and focally positive for CD34, supporting the diagnosis of SFT." (PMID 38982409, 2024). "We observed that interferon-alpha (IFN-α) and interferon-gamma (IFN-γ) very strongly induced the activation of the STAT1 protein, whereas IL-6 and IFN-α activated STAT3 and IL-4 activated STAT6 in all examined tumor cell lines." (PMID 38396958, 2024). "In oncology, STAT6 has emerged as a potential factor in tumor biology, with growing evidence suggesting its involvement in tumorigenesis and metastasis." (PMID 39353898, 2024). "This tumor sample showed positive immunoreactivity for STAT6 and CD34, while EMA was poorly expressed." (PMID 38341593, 2024). "Among these, the expression of STAT6 in the tumor cell is essential for diagnosis when CD34 and CD99 are negative." (PMID 39574987, 2024). "They released M2-targeted antagonists after exposure to the acidic tumor microenvironment, co-delivering inhibitors like STAT6 to effectively achieve M2-to-M1 repolarization, thereby inhibiting tumor growth and metastasis." (PMID 38650924, 2024). "MiR-210-3p is implicated in liver carcinogenesis and tumor angiogenesis through targets like SMAD4 and STAT6 and is driven by hypoxia-inducible factor 1α." (PMID 39456643, 2024). "The hallmark sign of the tumor is the NAB2::STAT6 fusion oncogene (NAB2: NGFI-A-binding protein 2; STAT6: signal transduction and activator of transcription 6)." (PMID 38392213, 2024). "STAT can act cooperatively, and the activation of STAT3 and STAT6 increases cathepsin expression in TAMs, promoting tumor invasion in vivo." (PMID 39516356, 2024). "Subsequently, to further elucidate the impact of STAT6 on UM in vivo, UM cells stably overexpressing STAT6 and control cells were separately injected into the subcutaneous tissue of nude mice, and tumor formation volume was monitored weekly." (PMID 39353898, 2024). "Our experimental results show that by binding to STAT6, GAN can regulate the M2 polarization of tumor-associated macrophages after suppressing the STAT6 phosphorylation, thereby inhibiting tumor progression." (PMID 38244580, 2024). "IL-4-driven activation of STAT6 inhibited TRIM24 activity, promoting the polarization of macrophages toward the tumor-associated phenotype in a murine model of melanoma." (PMID 39516356, 2024). "LncRNA-MM2P modulated M2 macrophages polarization by phosphorylating STAT6, thus promoting tumor angiogenesis and tumorigenesis." (PMID 39247822, 2024). "Silencing SNHG1 inhibited M2 macrophage polarization by suppressing STAT6 phosphorylation, thereby inhibiting tumor growth and angiogenesis." (PMID 39676873, 2024). "Activation of STAT1, STAT2, STAT3, STAT4, and STAT6 was observed in expanded bile duct epithelium and tumor cells, while expression of STAT5a and STAT5b was found in macrophages and connective tissues surrounding the tumor." (PMID 39290697, 2024). "This disparity between a purified single stimulus and the multifaceted nature of tumor-CM likely accounts for the observed outcome, highlighting the influence of the differing stimuli on the observed decrease in STAT6 phosphorylation." (PMID 39702544, 2024). "The tumor cells carry a NAB2:STAT6 gene fusion, which is a result of a paracentric inversion involving chromosome 12q13." (PMID 36805296, 2023). "Exosome‐mediated ASO suppresses STAT6 expression in TAM and causes effective reprogramming of TAMs to the M1 phenotype in CT26 and Hepa1‐6 tumor model." (PMID 38098217, 2023).
tumor (continued). "When we combined higher values of STAT1 and a value of STAT6 between 0.15 and 0.75 the macrophage will transit to a pro-tumor macrophage M2d." (PMID 37283734, 2023). "The presence of STAT6 in tumor cell nuclei is a highly sensitive immunohistochemical marker for SFT." (PMID 37315497, 2023). "Exosomes loaded with oligonucleotides targeting STAT6, a key transcription factor that regulates the polarization of M2-type macrophages, were delivered to tumor tissues to reprogram TAMs toward tumoricidal macrophages." (PMID 36978075, 2023). "This can be explained by the ability of tumor cells to hijack M2a cells to support their growth via the IL-4/STAT6-mediated pathway." (PMID 37108657, 2023). "In particular, the radiation-regulated miR-340/429/IL-4/β-catenin/Stat6 signaling axis effectively enhanced tumor progression and metastasis of human carcinomas." (PMID 36769373, 2023). "If STAT6 values are between 0.15 and 0.75 the M1 phenotype will transit to a pro-tumor M2d despite NFкB being present." (PMID 37283734, 2023). "In the immunohistochemistry for signal transducer and activator of transcription 6 (STAT6), a strong positive signal was observed in the nuclei of the tumor cells." (PMID 36805296, 2023). "Because IL-4 is implicated in secreting IL-10 and TGFB in the microenvironment due to the activation of STAT6, the M2a phenotype jumps to the tumor-promoting macrophage phenotype M2aM2cM2d hybrid." (PMID 37283734, 2023). "The presence of STAT6 in tumor cell nuclei is a highly specific and sensitive immunohistochemical marker for SFT and is useful for diagnosis." (PMID 37315497, 2023). "Several lines of evidence indicated that STAT6 transcriptional modulation regulates anti-tumor immunity, including phosphorylation, ubiquitination, and acetylation." (PMID 38264642, 2023). "When the M2c macrophage is in a microenvironment of tissue remodeling, when the values of STAT3 are between 0.35 and 0.65 and STAT6 are between 0.1 and 0.7 the macrophage will transit to a M2d phenotype with the capacity to regulate the growth of tumor cells." (PMID 37283734, 2023). "TAM from Stat6−/− tumor-bearing mice exhibits an M1 phenotype and shows enhanced rejection of different tumor types." (PMID 37670933, 2023). "This study illustrated that PS effectively suppress tumor progression and metastasis by inhibiting the polarization of M2 macrophages via the STAT6 signaling pathway, a novel mechanism of PS’s anti-tumor activity." (PMID 37175092, 2023). "Together with the impact on IL4-signalling via the JAK1/STAT6 axis, our data strongly support an early tumor suppressive role of miR-494-5p in CRC." (PMID 38201452, 2023). "The STAT6 expression plays a role in PCa cell proliferation and migration and was found to be positively correlated with the tumor size and high PCa histological grades." (PMID 37370685, 2023). "STINGVAX, a cancer vaccine comprising CDNs (activating TBK1/IRF3, NF-κB, and STAT6 signaling pathways) and GM-CSF, has shown promising results in different murine tumor models." (PMID 37380989, 2023). "There was significantly less STAT6 phosphorylation in Hepa1-6 cells induced tumor tissues from Mvp-/- mice than in Wt mice." (PMID 38264642, 2023). "Activation of the STAT6 signaling pathway is critical for the recruitment of immune cells and plays a central role in tumor initiation and progression." (PMID 36768437, 2023). "The impact of STAT6 inhibition on tumor progression was detected in Ph+ CML and Ph+ ALL mouse models." (PMID 36721266, 2023). "The positive reaction for STAT6 in the tumor nuclei constitutes a very highly sensitive and specific marker for SFT." (PMID 36805296, 2023). "Here, we show that humanized anti‐Chi3L1 antibody attenuated tumor growth and metastasis in vivo via STAT6‐dependent PLG signaling and M2 polarization inhibition." (PMID 34861103, 2022).